TSR3 (TSR3 ribosome maturation factor)
Description:
Aminocarboxypropyltransferase that catalyzes the aminocarboxypropyl transfer on pseudouridine at position 1248 (Psi1248) in 18S rRNA (Probable). It constitutes the last step in biosynthesis of the hypermodified N1-methyl-N3-(3-amino-3-carboxypropyl) pseudouridine (m1acp3-Psi) conserved in eukaryotic 18S rRNA (Probable).
Synonyms: HsTsr3; C16orf42; MGC24381
Tractability: PROTAC: ubiquitination databases record sites on it; its protein half-life has been measured.
Gene: Protein-coding gene on chromosome 16 (1,349,237 to 1,351,878, reverse strand). Ensembl gene ENSG00000007520.
Subcellular location: Cytoplasm
Subcellular location (Human Protein Atlas): Cytosol; Golgi apparatus
Pathways (Reactome):
Metabolism of RNA: rRNA modification in the nucleus and cytosol
Gene Ontology:
Molecular function: rRNA small subunit aminocarboxypropyltransferase activity; transferase activity; S-adenosyl-L-methionine binding
Biological process: enzyme-directed rRNA pseudouridine synthesis; maturation of SSU-rRNA; rRNA modification; rRNA processing
Cellular component: cytoplasm; cytosol
Genetic constraint (gnomAD): Loss-of-function variants: 32 observed, 25.98 expected, observed/expected ratio (o/e) 1.23, 90% interval 0.93 to 1.65. The synonymous counts are far from expectation, so gnomAD's model fits this gene poorly and the ratio says little. Missense variants: 511 observed, 404.2 expected, observed/expected ratio (o/e) 1.26, 90% interval 1.17 to 1.36. Synonymous variants: 219 observed, 176.32 expected, observed/expected ratio (o/e) 1.24, 90% interval 1.11 to 1.39.
Homologues: Orthologues: chimpanzee TSR3 (99% identical), macaque TSR3 (95% identical), pig TSR3 (83% identical), dog TSR3 (81% identical), rat Tsr3 (77% identical), guinea pig TSR3 (74% identical), mouse Tsr3 (70% identical), tropical clawed frog tsr3 (59% identical), zebrafish tsr3 (53% identical), Drosophila melanogaster CG4338 (41% identical), Caenorhabditis elegans F52C12.2 (32% identical).
Diseases named in the same sentence as TSR3 in open-access papers:
TSR3 is named in the same sentence as 3 diseases in open-access papers, as found by Europe PMC text mining. Sharing a sentence is not in itself a finding about the gene and the disease. The quoted sentences say what the papers report.
neuroblastoma (1 paper, 2026). Neuroblastoma (NB) is the most common solid, extracranial childhood tumor. "Complementary experiments in neuroblastoma cell lines reveal functional roles for TSR3 and WDR74 in mesenchymal-like tumor states." (PMID 41803115, 2026).
TSR3 also shares sentences with these, for which no sentence is quoted: cancer (1 paper); tumor (1).